MIR6070 (microRNA 6070)
Synonyms: hsa-mir-6070
Gene: MicroRNA gene on chromosome 21 (43,609,887 to 43,609,989, reverse strand). Ensembl gene ENSG00000278433.
Homologues: Orthologues: chimpanzee MIR6070 (100% identical).